MMP2 (matrix metallopeptidase 2)
Diseases named in the same sentence as MMP2 in open-access papers (continued):
Sharing a sentence is not in itself a finding about the gene and the disease.
cancer (continued). "Importantly, MMP2, MMP9 and MMP14 are enriched at the invadopodia and are required for cancer metastasis." (PMID 27789576, 2016). "Literature review expresses that overexpression and hyperactivity of MMP-2 and MMP-9 has been observed in pre-cancer and cancer lesions of all kinds of cancers including the uterine cervical cancer which is second most common malignant tumor among female in the developing countries." (PMID 27659937, 2016). "In an immortalized hepatocyte line, the MET protein, caveolins, and S100 family members in HCC-derived exosomes triggered PI3K/AKT and MAPK signaling pathways and increased the secretion of matrix metalloproteinase-2 (MMP-2) and MMP-9, thereby facilitating the invasion activity of cancer cells." (PMID 27463001, 2016). "They concluded that the inhibition of cancer cell invasion by cyanidin 3-glucoside or peonidin 3-glucoside, may be due to a downregulation of MMP-2, MMP-9 or u-PA expression of various cancer cells." (PMID 27548122, 2016). "In addition, Akt and other MAPK pathways are also reported to be coupled to MMP-2 and MMP-9 expression and play essential roles during cancer progression." (PMID 27057634, 2016). "Furthermore, EBV-miR-BART6-3p mimics inhibited metastasis and invasion-related genes, including MMP2 and MMP9 in three EBV-negative cancer cell lines." (PMID 27584792, 2016). "We observed in this study that both MMP-2 and MMP-9 protein levels and activity are downregulated in the presence of WJ-MSCs and fd-ECM, clearly showing that both MSCs and fd-ECM have an effect on “cancer survival” genes." (PMID 26880967, 2016). "The proteases MMP-2 and MMP-9 are known to favor the migration and invasion of cancer cells." (PMID 27282478, 2016). "Similarly, miR-29, miR-218, miR-340 and miR206 were reported to regulate MMP2 and MMP9 and these effects were also profound in cancer cells." (PMID 27992561, 2016). "Of the MMPs, MMP-2 and MMP-9, known as the gelatinases that degrade the main constituent of the basement membrane and type IV collagen, have been recognised as crucial in cancer invasion and metastasis." (PMID 26980735, 2016). "The activation of caspase-3 activity leads to cancer cells apoptosis, and survivin overexpression promotes the growth and drug resistance of cancer cells; Moreover, CXCR4 and MMP2/9 expression may play critical roles in promoting metastasis of HCC cells." (PMID 27716619, 2016). "B7-H3 had a close relationship with the T stage of cancer and was co-expressed with MMP2 and MMP9 in cancer tissues, which might originate from its ability to promote the EMT." (PMID 27145365, 2016). "Therefore, inhibition of MMP-2 and MMP-9 expression should be a high priority during cancer therapy." (PMID 26098839, 2015). "The overexpression of many MMP family members, such as MMP1, MMP2, MMP7, MMP9, and MMP11 has been found to be involved in cancer progression; therefore, the development of MMP inhibitors has become an effective strategy in clinical cancer therapies." (PMID 26084486, 2015). "Although MMP-2 and -9 have been demonstrated to play a central role in cancer metastasis in recent years, the trigonelline regulation of Hep3B cell migration is not mediated by the decrease in MMP-2 and -9 gene expression." (PMID 26699938, 2015). "In various cancer cells, TGF-β-induced EMT could upregulate the expression of MMP-2 and MMP-9, the two most critical enzymes, by activating the transcription factor Slug and Snail." (PMID 25879017, 2015). "Thrombin-mediated cleavage of PARs in cancer, blood cells, and vessel wall cells results in activation of transcription of many proangiogenic genes such as VEGF and its receptor (VEGFR), TF, MMP-2, angiopoetin-2 (Ang-2), basic fibroblast growth factor (bFGF), MAP, and PI3 kinases." (PMID 26573921, 2015).
cancer (continued). "MMP2 and MMP9 contain fibronectin repeats that help them recognize gelatin (denatured collagen) as a substrate and Type IV collagen is the main constituent of the BM, one of the first barriers that cancer cells need to traverse to metastasize." (PMID 25699257, 2015). "Inhibition of MMP-2 and MMP-9 activity can suppress cancer metastasis." (PMID 26304749, 2015). "Moreover, NF-κB expression in the nucleus contributes to the activation of MMP-2 and MMP-9, which play critical roles in cancer metastasis." (PMID 25394920, 2015). "Supplementation with the NM has beneficial effects in modulating cancer markers of proliferation (Ki67), invasion/metastasis (MMP-2 and -9), angiogenesis (VEGF), apoptosis (TUNEL and Bcl-2) and inflammation (COX-2 and iNOS), as well as the general cancer marker GSTπ." (PMID 25574189, 2015). "Furthermore, PI3K/AKT contributes to extracellular matrix destruction by increasing the production of MMP-2 and MMP-9 in many cancers." (PMID 25927939, 2015). "Moreover, nifuroxazide markedly blocked cancer cell migration and invasion, and the reduction of phosphorylated-Stat3Tyr705, matrix metalloproteinase (MMP) MMP-2 and MMP-9 expression were also observed." (PMID 25811798, 2015). "As a negative control, Catechin can also inhibit the growth of cancer cells, but has no inhibition effects on the migration and invasion of cancer cells, either the activity of MMP2 and MMP9." (PMID 26674531, 2015). "MMP-2 and MMP-9, two major MMPs, play important roles in cancer cell invasion and metastasis 35,36." (PMID 25753200, 2015). "The activity of MMPs, particularly MMP-2 and-9, on the degradation of the ECM plays a critical role in the formation of tumors and metastasis, and high MMP-9 levels have been found to correlate with the aggressiveness of cancers." (PMID 25574189, 2015). "AR, MMP-2 and MMP-9 may be predictive markers for HCC and could be regarded as candidates for indicating the cancer stage." (PMID 25667651, 2015). "As MMP2 and MMP9 were crucial proteins involved in cancer cell metastasis, we reasoned that SAE2 might regulate MMP expression in the SCLC." (PMID 26063074, 2015). "Specifically, BMAL1 has been shown to suppress cancer cell invasion by antagonizing the oncogene B-cell lymphoma w (Bcl-w), thus suppressing matrix metalloproteinase-2 (MMP-2) accumulation and blocking the PI3K-AKT-MMP2 signaling pathway." (PMID 26220712, 2015). "MMP-2 and MMP-9 have important roles in the invasion of cancer cells." (PMID 25633440, 2015). "Of the MMPs, MMP-2, MMP-9, and their upstream enzyme, urokinase-PA (u-PA), are the most vital enzymes for degrading the main constituent of the basement membrane, type IV collagen, and are deeply involved in cancer invasion and metastasis." (PMID 25605016, 2015). "MMP-2 and MMP-9 are key factors in cancer cell invasion and metastasis in vitro." (PMID 24520272, 2014). "Among these anti-cancer targets, 3-phosphoinositide-dependent protein kinase-1(PDPK1), MMP1, MMP2, MMP3, nitric oxide synthase (NOS2), and inosine-5′-monophosphate dehydrogenase 2 (IMPDH2) showed similar binding affinity with bruceantin as that of some marketing drugs." (PMID 24429698, 2014). "In addition, it has been shown that MMP-2 and MMP-9 levels in radical prostatectomy specimens were significant predictors of cancer recurrence." (PMID 24978435, 2014). "One possible mechanism through which KY-05009 inhibits invasion could be through its attenuation of TGF-β1-induced expression and activation of MMP-2 and MMP-9 via NF-κB, which is a well-known transcription factor that controls cancer metastasis." (PMID 25337707, 2014). "Unlike in HBE cell lines, both MMP2 mRNA and protein were overexpressed in these three cancer cell lines as indicated by the observed PCR products at the expected size of 180 bp and the specific protein binding band at the expected size of 72 kDa." (PMID 25000246, 2014).
cancer (continued). "Our data also propose that nucleotides released from metastatic cancer cells induce the recruitment of inflammatory cells including macrophages or monocytes via P2Y2R and that P2Y2R activation in monocytes mediates the secretion of MMP-2 and -9." (PMID 25238333, 2014). "For other genes or regions, e.g. DLX5, GRASP Region 3, IRX1, MMP2, NPY, PDX1 and TCF21, significant levels of methylation were evident in the matched normal tissue but methylation was always significantly increased in the cancer tissue." (PMID 24485021, 2014). "Moreover, α-mangostin reduced both the mRNA and protein levels of MMP-2 and MMP-9, which play critical roles in migration, invasion, and metastasis of cancer cells." (PMID 24812621, 2014). "MMP2 and MMP9 have been shown to play important roles in cancer cell invasion and metastasis." (PMID 24479681, 2014). "Moreover, verrucarin A was able to inhibit expression of the SRC-3 target genes MMP2 and MMP13 and attenuated cancer cell migration." (PMID 24743578, 2014). "We observed that HCS prevented the invasion of cancer cells, with inhibiting the expressions of MMP-2 and MMP-9, and reduced not only the number of metastasis nodules but the ratio of liver-body weight as well." (PMID 25496480, 2014). "Matrix metalloproteinase-2 (MMP-2) and matrix metalloproteinase-9 (MMP-9) are highly expressed in various malignant tumors and are involved in the degradation and breakdown of the environmental extracellular matrix (ECM) and the basement membrane, promoting cancer metastasis." (PMID 25222667, 2014). "Furthermore, TGF-β1 induced the transcriptional activity of NF-κB, which is a transcription factor that regulates MMP-2 and MMP-9 expression, and is well-known to play a role cancer metastasis; KY-05009 also attenuated this effect in a dose-dependent manner." (PMID 25337707, 2014). "In our study, we sought to determine whether MMP-2 and/or MMP-9 expression differed between aggressive cancers on the positive margin of the resection that progress and cancers that remain localized." (PMID 25097794, 2014). "Otherwise, as recently reported in human cancers, Wnt5a/Ror2 signaling may up-regulate the expression of matrix metalloproteinases (MMPs) such as MMP1, MMP2, and MMP13 to increase cell invasiveness." (PMID 25211363, 2014). "Curcumin successfully down regulated the MMP-2, -9 and TIMP-1, -2 to maintain the net balance of MMPs/TIMPs to inhibit, at least in part, cancer cell invasion and migration in HT1080 human fibrosarcoma cancer cells." (PMID 25566531, 2014). "In addition to EMT, deregulation of the extracellular matrix (ECM) and basement membrane by matrix metalloproteinase (MMPs), such as, MMP2, MMP9 is thought to play a key role in cancer cell invasion and metastasis." (PMID 24885825, 2014). "A previous study of the comparative effects of NM, green tea extract and EGCG on the inhibition of MMP-2 and MMP-9 secretion in various cancer cell lines with varying MMP secretion patterns, revealed the superior potency of NM over green tea extract and EGCG at equivalent doses." (PMID 24669274, 2014). "MMP2 and MMP9 were identified to exert crucial effect as the indicators in cancer progression." (PMID 24023875, 2013). "Our findings are consistent with previous studies using animal models of cancer that indicated that MMP-2 apparently does not significantly contribute to the angiogenic switch." (PMID 24392031, 2013). "The suppression of the matrix metalloproteinases MMP2 and MMP9 and the inhibition of the enzymatic activities of these metalloproteinases further confirmed the antimetastatic and antiinvasive activities of HCA in highly metastatic cancer cells." (PMID 23860239, 2013). "Therefore, MMP-2, MMP-9 and u-PA, which are secreted by invasive cancer cells, are considered to be important in cancer cell invasion and metastasis because of their roles in the degradation of the ECM." (PMID 24039823, 2013).
cancer (continued). "In particular, the secreted MMP-2 and MMP-9 are important molecules in cancer cell invasion." (PMID 23864892, 2013). "While the exact mechanism underlying these changes is not clear, it may be related to the control of MMP expression as Snail2 mediates the upregulation of MMP2 and MMP9 in a range of other cancers." (PMID 23352643, 2013). "Taken together, overexpression of basigin-2 increased the secretion of MMP-2/MMP-9 and cancer cell migration and invasion of HO-8910 cells, whereas the inhibition caused by basigin-2 siRNA affected HO-8910PM cell migration and invasion through MMP-2 and MMP-9 expression." (PMID 23566400, 2013). "It was observed that treatment of NSCLC cells with honokiol degraded cytosolic β-catenin, reduced nuclear accumulation of β-catenin and down-regulated matrix metalloproteinase (MMP)-2 and MMP-9, which are the down-stream targets of β-catenin and play a crucial role in cancer cell metastasis." (PMID 23580348, 2013). "Furthermore, the present study verified the expression of the cancer invasion-related genes, MMP-1, MMP-2, EGFR and COX-2, which were upregulated in the CD44+ GC cells, indicating a capacity to manipulate cancer invasion and even metastasis." (PMID 23833643, 2013). "Taken together, the elevated ZEB1 expression following EMT may serve as an important mediator that could converge highly activated EGFR-MEK/ERK signaling on MMP2 induction, facilitating the invasion of the EMT-induced cancer cells." (PMID 24318272, 2013). "MMP2 and MMP9 are involved in intravasation by participating in extracellular matrix (ECM) conversion and remodeling through hydrolyzing major protein components when cancer cells must exit the blood vessels, lymphatics and constricted capsules." (PMID 24023875, 2013). "A previous study of the comparative effects of NM, green tea extract and EGCG on inhibition of MMP-2 and MMP-9 secretion of different cancer cell lines with varying MMP secretion patterns, revealed the superior potency of NM over GTE and EGCG at equivalent doses." (PMID 23661254, 2013). "For example, a previous study of the comparative effects of NM, green tea extract and EGCG on inhibition of MMP-2 and MMP-9 secretion of different cancer cell lines with varying MMP secretion patterns, documented the superior potency of NM over GTE and EGCG at equivalent doses." (PMID 22736175, 2012). "MMP2 and MMP9 are key enzymes involved in angiogenesis during cancer development." (PMID 23206527, 2012). "Therefore, it appears that FAK can promote CL1-5 cancer cell migration through the MAPK signaling and MMP-2 and MMP-9 pathway." (PMID 22454661, 2012). "Moreover, sLRP6E1E2 reduced expression of MMP-2/MMP-9, which correlate with tumorigenicity and metastatic potential of cancer cells." (PMID 22606268, 2012). "RECK decreases the amount of active MMP-2 and MMP-9 in conditioned medium and inhibits metastatic activity in vitro and in vivo through modulation of these MMPs, which are known to be involved in cancer progression." (PMID 22642976, 2012). "MMP-2 and MMP-9 play important roles in the degradation of the ECM, including type IV collagen, and their activity and expression are correlated with metastatic abilities and prognosis of cancer." (PMID 22420896, 2012). "The inhibition of MMP-2 decreases the ability of the cancer to migrate from its new site, but does not inhibit proliferation directly." (PMID 23227342, 2012). "There was concordance in MMP-2 expression between CPCs and DTCs but not with mM for all Gleason scores in men with nonmetastatic cancer." (PMID 23227342, 2012). "In addition, some MMPs including MMP-1, MMP-2 and MMP-13 are involved in Wnt-5a mediated invasion of cancer cells." (PMID 21998657, 2011). "Both MMP-2 and MMP-9 play important roles in the pathogenesis of many cancers." (PMID 21909361, 2011).
cancer (continued). "These genes were not included in our original dataset either because they were not in the "Cancer Gene Census" category of COSMIC (MMP2, PIK3C3, TGM3, EPHA3) or because there was no crystal structure available (DCLK3)." (PMID 21575214, 2011). "However, previous studies have demonstrated that MMP-2 can be up-regulated by some stimuli such as TGF-β, but usually participates in development of cancer including growth, invasion, and metastasis." (PMID 21134288, 2010). "Among members of the MMP family, MMP-2 (gelatinase-A) and MMP-9 (gelatinase-B) are particularly up-regulated in malignant tumors and contribute to the invasion and metastatic spread of cancer cells by degrading type IV collagen, a major component of the basement membrane." (PMID 20525232, 2010). "As the expression of MMP2 is also known to be stimulated by HB-EGF in carcinoma cells, we next determined whether as-APF also regulated MMP2 expression in T24 cells." (PMID 21143984, 2010). "Similarly, E-cadherin has been reported to transcriptionally regulate a variety of integrins and matrix metalloproteases (MMP1, MMP2, MMP3, MMP14 and TIMP-1) in other cancer models." (PMID 19257890, 2009). "As observed for recombinant proMMP-2, latent and active MMP-2 secreted by cancer cells also did not bind to BSP." (PMID 19386107, 2009). "Such anti-cancer activities of BER involved suppression of Akt and NF-κB signaling and its upstream and downstream targets by reducing expressions of the related proteins and mRNA as well as pro-MMP-9/pro-MMP-2 activation in the cells." (PMID 19796390, 2009). "In conclusion, our findings raise the possibility that EGCG could inhibits cancer cell invasion through reversal of hypermethylation status of RECK and downregulation of MMP-2 and MMP-9." (PMID 18665171, 2008). "Treatment with 50 μM EGCG did not cause downregulation in MMP-9 activity but MMP-2 in HSC4 and SCC25 cancer cell line (data not shown)." (PMID 18665171, 2008). "MMP-13 detected either in cancer cells or in adjacent fibroblasts, was not correlated with MMP-2 or MMP-9." (PMID 18373849, 2008). "Clinical studies suggest that TIMP-2, or the ratio of MMP-2 and TIMP-2 expression, may play a critical role on cancer progression." (PMID 16776850, 2006). "Its relevance in cancer is doubtful because these differences are seen in normal tissue only, where activities are very low, and do not pertain to active MMP-2." (PMID 12085179, 2002). "MMP-2 mRNA expression was noted in fibroblasts surrounding the carcinoma cells, and no signal in carcinoma cells was detected." (PMID 9649139, 1998). "Metalloproteinases (MMP-2 and MMP-9) are involved in the destruction of the extracellular matrix, and their increased expression may increase the migration and invasive potential of cancer cells." (PMID 39352533, 2025). "qPCR analyses revealed that RLN2-secreting CAR-T cells, particularly activated cells, induced MMP-2 and MMP-9 expression, though at lower levels than that in cancer cells, suggesting that the primary mechanism of stromal dissolution by RLN2-secreting CAR-T cells is paracrine, acting on cancer cells." (PMID 40666525, 2025). "Its degradation, in particular under the action of MMP-2, also called type IV A collagenase, affects the integrity of the basement membrane, favouring invasiveness, neovascularisation and metastasis, which are negative prognostic factors in all cancers." (PMID 40724562, 2025). "Also, matrix metalloproteinase 2 (MMP2) is an enzyme located outside cells that contributes to the development, expansion, and metastasis of tumors, which are more prevalent in various types of cancer." (PMID 40837737, 2025). "PAPPA (nonhub) and MMP2 (hub) have been introduced as cancer biomarkers." (PMID 39854135, 2025).